WNT3 (Wnt family member 3)
Diseases named in the same sentence as WNT3 in open-access papers (continued):
Sharing a sentence is not in itself a finding about the gene and the disease.
tumor (continued). "Western blot analysis showed that Wnt3, Wnt3a and Wnt10a were indeed expressed in the tumor grafts, and their expression levels were higher than those in normal subcutaneous tissue and normal mouse colon." (PMID 28147310, 2017). "When GCP-like tumor cells were incubated with WNT3, we noted increased expression of TAG1 and TUJ1, markers of differentiation." (PMID 24303070, 2013). "Similar results were obtained when YFP positive cells selected by FACS were injected into athymic nude mice, indicating that WNT3 inhibited tumor growth." (PMID 24303070, 2013). "Several positive-acting ligands for this pathway, including Wnt3, Wnt3a, Wnt7b, and Wnt5a, are significantly overexpressed in tumor tissue, and mRNA for Wnt3 is about 5-fold more abundant in transgenic mammary tissue than in non-transgenic mammary tissue." (PMID 21304988, 2011). "Erianin may exert its anti-tumor effect in DDP-resistance LUAD cells by regulating the Wnt3/β-Catenin/Survivin/Bcl-2/Caspase3/Cyclin D1 axis." (PMID 39605083, 2024). "Erianin may exerted its anti-tumor effect in DDP-resistant LUAD cells by regulating the Wnt3/β-Catenin/Survivin/Bcl-2/Caspase-3/Cyclin D1 axis." (PMID 39605083, 2024). "We, therefore, speculate that GC cells require not only increased Wnt3 expression levels for tumour maintenance but that increased Flot2 expression allows more effective ligand dissemination in the tumour tissue." (PMID 36040316, 2022). "Indeed, the treatment of 5-FU increased the mRNA level of Wnt3 in tumor organoids derived from ApcMin/+/Lgr5EGFP mice." (PMID 33087710, 2020). "We found that overexpression of Wnt3 promoted the tumor growth obviously in nude mice." (PMID 31632267, 2019). "We found that Wnt3 upregulation resulted in a significantly accelerated tumor growth." (PMID 31632267, 2019). "In addition, high Wnt3 expression level is correlated with tumor grade, age, drink status, and FOBT results." (PMID 31632267, 2019). "In GC, overexpression of Wnt ligands (Wnt2, Wnt3, and Wnt5A) and receptors (FZD7 and LRP5/6) is associated with more advanced disease, poorer prognosis, and elevated metastatic potential, while β-catenin and reduced APC expression further underline more aggressive tumor behavior." (PMID 40943055, 2025). "The data demonstrated that downregulation of Wnt3 could inhibit cellular proliferation and colony formation due to cell cycle arrest in G1/S phase, suppress cellular migration ability, and inhibit tumor growth in vivo, through antagonizing the canonical Wnt signaling pathway." (PMID 31632267, 2019). "Therefore, it seems that SOX9 and c-myc might play more dominant roles than ERBB2 and WNT3 in determining tumor stemness in this tumor model." (PMID 25003837, 2014). "EC is characterized by elevated expression of multiple Wnt ligands (notably Wnt2, Wnt3, Wnt5A, and Wnt6) and FZD receptors, often correlating with poorer differentiation, higher potential of tumor invasion, and shorter survival." (PMID 40943055, 2025). "In HNSCC xenograft and mouse mammary tumor virus (MMTV)-driven Wnt1 and Wnt3 tumor models, daily injections of LGK974 led to significant tumor regression." (PMID 38612911, 2024). "The expression of hsa-miR-374a-3p decreased gradually in tumor-adjacent, COAD, and hepatic metastasis tissues, while WNT3 and β-catenin showed opposite trends." (PMID 35837105, 2022). "The results showed that hsa-miR-374a-3p was downregulated gradually in the tumor-adjacent, COAD, and hepatic metastasis tissues, while the expression of WNT3 and its downstream molecule β-catenin showed the opposite trend." (PMID 35837105, 2022). "To this end, we checked if there was differential expression of Wnt ligands including WNT1, WNT3 and WNT10B among normal liver and HCC tumor tissues." (PMID 35003366, 2021).
tumor (continued). "Further analysis of the correlation between the WNT gene family and clinicopathological parameters of UCEC showed that the WNT1, WNT3, WNT7A, WNT7B, WNT8B, and WNT10A genes were expressed at significantly different levels at different tumor stages." (PMID 34565373, 2021). "According to our observation, overexpression of Wnt3 in CRC cell line accelerated the cellular proliferation and tumor growth in nude mice, through activating the β-catenin-dependent target oncogenes like c-Myc and cyclin D1 in Wnt signaling." (PMID 31632267, 2019). "Conversely, suppression of endogenous Wnt3 in CRC cells inhibited cellular proliferation, migration, and tumor growth and promoted the apoptosis under cisplatin, through inhibiting the canonical Wnt pathways and glycolysis." (PMID 31632267, 2019). "Tumor stroma-derived WNT ligands like WNT3 and WNT5B are critical factors that instigate invasive behavior, and induction of an EMT phenotype in tumor epithelial cells." (PMID 31324218, 2019). "WNT3 YFP-expressing tumors also contained a reduced number of YFP positive cells, suggesting that the decrease in tumor growth was due to a decrease in proliferation of WNT3-YFP infected cells." (PMID 24303070, 2013). "miR-34a was also reported to target Notch signaling pathway to inhibit tumor stem cell invasion by directly binding to NOTCH1, DLL1 and JAG1 as well as Wnt signaling pathway by targeting WNT1 and WNT3 genes and TGF-β signaling pathway via Smad4." (PMID 23823624, 2013). "For example, tumor C3H BF had Wnt1 as a CIS in addition to Tcf7l2, while insertion of MMTV at Antxr1 and Wnt3 in tumor Balb 5 resulted in the expression of both CISs." (PMID 22087314, 2011). "However, the effect of WNTs on tumor purity in LUSC was slightly poorer than that in LUAD, and WNT3/5A/8B/11 were positively correlated with tumor purity, while WNT1/2/4/6/7A/98/10A were negatively correlated with tumor purity." (PMID 35957916, 2022). "PC-specific deletion of Wnt3 (PC-Wnt3−/−) led to reduced tumor count in the small intestine without a change in tumor area or a change in tumor phenotypes in the colon." (PMID 33372038, 2021). "In cancer cells, linc00662 has been shown to upregulate WNT3 through binding miR-15a/16/107, activating the WNT/β-catenin signaling pathway, increasing proliferation and migration abilities of tumor cells in vitro, and promoting tumor growth in vivo." (PMID 34439281, 2021). "To explore the role of Wnt3 in tumorigenesis of CRC, we examined Wnt3 expression levels in human CRC tissues and paired normal colorectal tissues, as well as the effects of dysregulation of Wnt3 on CRC cellular activities and tumor formation in nude mice." (PMID 31632267, 2019). "Furthermore, knockdown of Wnt3 in CRC cells suppresses CRC cell growth, migration, and tumor growth and induces the apoptosis and drug sensitivity of CRC cells." (PMID 31632267, 2019). "To determine the expression of Wnts in non-CRC cell types in the tumor grafts, we sorted host-derived endothelial cells, fibroblasts, macrophages and dendritic cells and tested mRNA levels of Wnt3, Wnt3a, Wnt5a and Wnt10a in these cells." (PMID 28147310, 2017). "To assess whether WNT3 suppresses tumor growth in vivo, we infected tumor cells with retroviruses expressing YFP alone or WNT3 and YFP (WNT3-YFP) and injected them sub-cutaneously in the flank of athymic nude mice." (PMID 24303070, 2013). "WNT3 is probably involved in the development of drug resistance of MM cells by an autocrine mechanism, and WNT3A may contribute to the proliferation of tumor cells." (PMID 40650009, 2025).
tumor (continued). "Wnt3 expression was decreased in the absence of LAT1 in the intestinal epithelium, suggesting that loss of Paneth cells due to LAT1 deficiency reduced the risk of tumor initiation by decreasing Wnt3 production." (PMID 36739585, 2023). "It would be acceptable to explain that the tumor number was not affected because the colon lacks Paneth cells; our data is further supported by a previous report, which showed Paneth cell-specific deletion of Wnt3 blocked ApcMin/+ tumor formation in the small intestine but not in the colon." (PMID 36739585, 2023). "To explore whether WNT3 induction is responsible for the activation of the WNT/β-catenin signaling pathway and subsequent CSC activation in 5-FU-treated CRC, we treated tumor organoids derived from ApcMin/+/Lgr5EGFP mice with porcupine inhibitor LGK-97432 and 5-FU." (PMID 33087710, 2020). "However, this study analyzed the presence of mRNA only in tumor cells, but not in BM cells, and it is not known whether the paracrine transmission of WNT3 to MM cells from MSCs has the same effect." (PMID 37239457, 2023). "Our results showed that MCL-ICs were enriched in Wnt3 compared to MCL-non-ICs and B-cells, irrespective of total tumor Wnt3 expression." (PMID 26048374, 2015).
cancer (34 papers, 2009 to 2026). A tumor composed of atypical neoplastic, often pleomorphic cells that invade other tissues. "In recent years, the Wingless and Int-1 (WNT) signaling pathway has been increasingly studied in cancer drug resistance; however, the role of WNT3, a ligand of the canonical WNT signaling pathway, in OSCC 5FU-resistance is not clear." (PMID 38711026, 2024). "Many studies have investigated WNT3 in relation to other types of cancer and their chemotherapy resistance." (PMID 38711026, 2024). "The hyperactivation of Wnt3 critically modulates lung tumorigenesis by enhancing proliferation, migration, and invasion with the concomitant inhibition of apoptosis in cancer cells." (PMID 37110139, 2023). "Here, we highlight two interesting examples, ABO and WNT3, both are shared by COVID-19 with more than one investigated cancer." (PMID 37636041, 2023). "The elevated expression of THBS1 and WNT3 genes confers cancer cell resistance to therapies through diverse mechanisms." (PMID 36139614, 2022). "In the cancer cell lines, Wnt3 localisation was enriched on these filopodia and more often detectable." (PMID 36040316, 2022). "Our data provide the first evidence that Wnt3 localises to cytonemes and cytoneme-delivered Wnt3 can induce paracrine Wnt/β-catenin transduction cascade to promote cancer stem cell activity and proliferation of GC cells." (PMID 36040316, 2022). "Gastric epithelial normal and cancer cell lines utilise cytonemes to transport Wnt3 intercellularly." (PMID 36040316, 2022). "We performed this CF assay to determine if paracrine Wnt3 was being transmitted by cytonemes to functionally regulate the ability of receiving AGS cells to activate cancer stem cell activity." (PMID 36040316, 2022). "The expression levels of Wnt3 in A549 cancer cells were 0.74, 0.51, and 0.31 upon treatment with 50, 100, and 200μm FDN, respectively, compared to untreated cells." (PMID 35054507, 2022). "These cancers can be caused by single mutations (germline or mosaic) in, for example, APC or WTX, but also common genetic variation in WNT3, DVL1, and NXN is previously associated with increased cancer risk." (PMID 32328030, 2020). "Among various Wnts associated with the canonical Wnt/-catenin signaling pathway, Wnt3 was previously reported being frequently up-regulated in human cancers." (PMID 30814912, 2019). "Wnt3, as a member of Wnt family, has been proved to promote the stabilization of β-catenin to regulate the radiation sensitivity of cancer cells." (PMID 31851619, 2019). "The strategy was to transiently express either Wnt3 or Wnt7a in A549 cells, isolate total RNA, and screen for miRNA expression by using a cancer-specific miRNA super-array." (PMID 23862015, 2013). "While LOI of IGF2 leads to cancer through upregulation of the Wnt3 pathway." (PMID 41890909, 2026). "These relationships suggest that estrogen may modulate gene regulation and activate pathways, such as WNT3, contributing to the progression of both cancers." (PMID 40564925, 2025). "Consequently, we posited that our study substantiates, at least in part, the role of PMAIP1 in regulating the cancer progression of FTC via modulation of the Wnt3/FOSL1 pathway." (PMID 39944827, 2025). "Finally, dysregulation of Wnt3/β-catenin/GSK-3β axis is linked to a wide range of illnesses, including cancer, kidney disease, bone problems, and neurodegenerative diseases." (PMID 36015156, 2022). "Therefore, the inhibition of metastasis via downregulation of Wnt-3 will be a valuable strategy in cancer treatment." (PMID 33014112, 2020). "However, recent researches demonstrated that Wnt3 was down-regulated in some types of cancers and related to worse prognosis." (PMID 30814912, 2019).
cancer (continued). "Conversely, the cancer cell–derived WNT7A, WNT7B, and WNT10A and stromal WNT3 and WNT9A were highly expressed in the squamous subtype." (PMID 35536676, 2022). "(D) Quantification of Wnt3-positive filopodia in gastric epithelial (HFE-145) and cancer (AGS) cells as a percentage of total filopodia (number of cells analysed = 6, 8, 6)." (PMID 36040316, 2022). "WNT3, a ligand in the WNT signaling pathway that drives canonical WNT/β-catenin signaling through autocrine or paracrine mechanisms, plays an important role in various biological activities, and has been studied in the context of drug resistance in other cancers." (PMID 38711026, 2024).
infection (5 papers, 2016 to 2018). The state of being infected such as from the introduction of a foreign agent such as serum, vaccine, antigenic substance or organism. "A group of Treg-signature genes (Areg, Arhpag20, Bub1b, Ccl12, Ccr5, Il1r1, Mki67 (Ki67) Ncf1, Nrp2, Tnfrsf9, Tcf19, Uhrf1, and Wnt3) were expressed at higher levels in IFNARfl/fl x Foxp3YFP-Cre mice than WT controls on day 5 Armstrong infection." (PMID 29672594, 2018). "We found that after infection with H9N2 virus, RT-qPCR measurements of the relative mRNA transcript level of Wnt3 was significantly reduced at 48 hpi." (PMID 29096712, 2017). "The infected mice exhibited increased mRNA levels of canonical (Wnt1, Wnt2, Wnt3, and Wnt3a) and noncanonical (Wnt5a) Wnt molecules, receptors (Fz1 and Fz5) and the Wnt signalling target gene Sox9 in hepatocytes at 6 and 12 weeks post-infection." (PMID 28331224, 2017). "Although the mRNA transcript levels of Wnt3 and Axin2 in mouse intestinal organoids were not significantly altered after infection with H9N2 virus for 1 or 12 h, the expression level of Wnt3 was significantly reduced at 48 h." (PMID 29096712, 2017).
neurodegenerative disease (3 papers, 2022 to 2023). A disorder of the central nervous system characterized by gradual and progressive loss of neural tissue and neurologic function. "Moreover, HUGO: SFRP1 and WNT3 genes probably play a role in the canonical Wnt/β-catenin signaling pathway, an essential constituent in the progress of neurodegenerative diseases." (PMID 37427327, 2023).
WNT3 also shares sentences with these, for which no sentence is quoted: Alzheimer disease (3 papers); bladder exstrophy (2); cleft lip (2); cleft palate (2); colon adenocarcinoma (2); lung squamous cell carcinoma (2); orofacial cleft (2); adenocarcinoma (1); atrial fibrillation (1); basal cell carcinoma (1); behavioral disorders (1); carcinoma of the digestive system (1); CATSHL syndrome (1); Cerebral ischemia (1); chronic myeloid leukemia (1); cognitive decline (1); colon adenoma (1); embryonal carcinoma (1); epispadias (1); esophageal cancer (1); essential hypertension (1); exstrophy-epispadias complex (1); glioblastoma (1); hypothyroidism (1); idiopathic pulmonary fibrosis (1); kidney disease (1); leukoplakia (1); lip (1); liver cancer (1); lung adenocarcinoma (1).
A further 20 diseases each share a sentence with WNT3 in 1 paper.